RASSF1 (Ras association domain family member 1)
Diseases named in the same sentence as RASSF1 in open-access papers (continued):
Sharing a sentence is not in itself a finding about the gene and the disease.
prostate carcinoma (continued). "In some cancer there are some epigenetic markers that has been discovered due to the fact that prostate cancers frequently contain methylation of the tumor suppressor genes GSTP1, RASSF1, and APC, these genes are regarded as cancer biomarkers." (PMID 39132504, 2024). "Intuitive and biologically interpretable methylation state thresholds are inferred and DMCs are identified, including those related to genes such as GSTP1, RASSF1 and RARB, known for their role in prostate cancer development." (PMID 39661598, 2024). "We included primers for four genes in the pre-amplification pool (RASSF1, APC, RARB and GSTP1), which have previously been identified as being methylated in a large percentage of prostate cancers." (PMID 35272673, 2022). "Methylation biomarkers have been identified in prostate cancer previously, including promoter segments of GSTP1, RASSF1, and APC, which are used in commercial tissue-based test to identify patients needing repeat biopsies after an initial negative biopsy." (PMID 28412973, 2017). "We identified five highly methylated genes in prostate cancer: GSTP1, RARB, RASSF1, SCGB3A1, CCND2 (P < 0.0001), with an area under the ROC curve varying between 0.89 (95 % CI 0.82–0.97) and 0.95 (95 % CI 0.90–1.00)." (PMID 27576364, 2016). "Our preliminary results, obtained in a single-institution study with limited enrolment, showed that the hypermethylation of GSTP1, RARB, RASSF1, SCGB3A1 and CCND2 was highly tumour-specific in prostate cancer tissue." (PMID 27576364, 2016). "Our preliminary results highlighted that hypermethylation of GSTP1, RARB, RASSF1, SCGB3A1 and CCND2 was highly tumour-specific in prostate cancer tissue." (PMID 27576364, 2016). "An initial test cohort of 30 prostate cancer-positive samples and 12 cancer-negative samples was used as basis for the development and optimization of an epigenetic multiplex assay based on the GSTP1, APC and RASSF1 genes, using methylation specific PCR (MSP)." (PMID 22672250, 2012).
ovarian carcinoma (39 papers, 2007 to 2025). A malignant neoplasm originating from the surface ovarian epithelium. "RASSF1 is commonly silenced by promoter hypermethylation in a variety of types of human cancer, including ovarian cancer." (PMID 24179489, 2013). "CDH13, glutathione S-transferase-π1 (GSTP1) and RASSF1 are frequently methylated in sporadic and BRCA1-associated ovarian cancers." (PMID 24179489, 2013). "We previously identified that methylation of three genes (MINT31, RASSF1, and CDH13) was significantly associated with Her2/neu overexpression in ovarian carcinoma from the United States." (PMID 22925189, 2012). "Previous studies have indicated that RASSF1 is frequently methylated in breast, lung and ovarian cancers." (PMID 23226780, 2012). "We previously identified methylation of three ovarian carcinoma-specific genes (MINT31, RASSF1, and CDH13) significantly associated with Her-2/neu overexpression." (PMID 22925189, 2012). "A large number of putative suppressor genes that are silenced or activated by aberrant methylation have been identified in ovarian cancer, including hypermethylation of OPCML, RASSF1, CDKN2B as well as classical tumor suppressors BRCA1, p16 and MLH1, and hypomethylation of LINE-1, SLC6A12 and PRAME." (PMID 35710397, 2022). "For two genes, RASSF1 and FOXL2, the patients who died of the ovarian carcinoma showed a statistically higher mean of methylation compared to the patients who were still alive (M-value of 6.63 vs. 4.16 for FOXL2 and 6.43 vs. 5.17, for RASSF1; p < 0.05)." (PMID 29882921, 2018). "In ovarian cancer, aberrant methylation of CpG islands in tumor suppressor genes, including CDKN2B, BRCA1, APC, RASSF1, and CDH13, is a frequent event compared to that in the normal ovarian surface epithelium." (PMID 31615043, 2019).
melanoma (38 papers, 2009 to 2025). A malignant, usually aggressive tumor composed of atypical, neoplastic melanocytes. "There are at least 5 RASSF1 splice isoforms transcribed from different promoters but we find that only the A and C isoforms are expressed in melanomas." (PMID 19949544, 2009). "Among the tumour suppressor genes with frequent promoter hypermethylation in melanomas, causing repression of transcription, are CDKN2A, Ras association domain family member 1 (RASSF1A), and PTEN, with the latter two particularly becoming hypermethylated in later stages of the disease." (PMID 34680938, 2021).
hepatocellular carcinoma (34 papers, 2006 to 2025). A malignant tumor that arises from hepatocytes. "Older Gnmt−/− mice develop hepatocellular carcinoma associated with hypermethylation of RASSF1 (Ras association domain family member 1) and SOCS2 (suppressor of cytokine signaling 2) promoters, and silencing of the respective genes." (PMID 31208147, 2019). "We find a matching association of RASSF1A and SRF in hepatocellular carcinoma (TCGA; P < 0.0001), again with significant linear correlation of RASSF1/SRF transcripts (R = 0.29) and further correlations with bladder and colorectal cancer (Fig EV6)." (PMID 31414556, 2019). "Indeed, in hepatocellular carcinomas (HCC) the adenomatous polyposis coli (APC) and RASSF1 tumor suppressor genes were hypermethylated and the MEST gene was hypomethylated." (PMID 35215560, 2022).
gastric cancer (33 papers, 2007 to 2025). A primary or metastatic malignant neoplasm involving the stomach. "UA inhibits gastric cancer (GC) cell proliferation and metastasis through activating Hippo signaling via RASSF1 and exhibits antitumor activity." (PMID 37799806, 2023). "Collectively, UA diminishes the proliferation and metastasis of gastric cancer via the regulation of Hippo pathway through Rassf1, which suggests that UA can be used as a potential chemopreventive and therapeutic agent for gastric cancer." (PMID 31547587, 2019). "UA significantly induced the protein expression levels of RASSF1 and the expression of phosphorylated Yap, an inactive form of Yap, in a dose-dependent manner in gastric cancer cells." (PMID 31547587, 2019). "The p-YAP expression induced in gastric cancer cells by UA was reversed with RASSF1 silencing." (PMID 31547587, 2019). "Similar to the gene expression profiling results, the protein levels of RASSF1, MST1, MST2, LATS1, and p-YAP were increased, whereas those of CTGF were decreased by UA in gastric cancer cells." (PMID 31547587, 2019). "In gastric cancer, a large number of genes (e.g., CDKN2A, CDK2AP2, CDH1, MGMT, RASSF1, RUNX3, and DLC1) have been shown to be suppressed by CpG island hypermethylation." (PMID 23179365, 2013). "We further tested whether UA treatment could facilitate RASSF1 using a silencing experiment with RNA interference in SNU484 and SNU638 cells because UA suppresses gastric cancer cell proliferation by regulating the Hippo signaling pathway." (PMID 31547587, 2019). "Further, in gastric cancer, as EBV-induced hypermethylation targets and silences key tumor suppressor genes including APC, RASSF1, BRCA1, THBS1, and CDKN2A, DNA methyltransferase inhibitors may also serve as a new therapeutic treatment for patients with EBV-positive gastric cancer." (PMID 37234978, 2023).
colorectal cancer (31 papers, 2007 to 2025). A primary or metastatic malignant neoplasm that affects the colon or rectum. "This study identifies specific genetic variants (RASSF1 rs2073498, SERPINE1 rs1799889, and EFNA1 rs12904) associated with colorectal cancer in the Mexican population and highlights their value as potential biomarkers for late-stage prognosis." (PMID 40004552, 2025). "In conclusion, the analysis reveals a significant association between the genetic variants RASSF1 (rs2073498), SERPINE1 (rs1799889), and EFNA1 (rs12904) and colorectal cancer, highlighting their potential as valuable genetic markers." (PMID 40004552, 2025). "In conclusion, our results demonstrated that SKP1 promotes YAP-mediated colorectal cancer stemness via degradation of RASSF1." (PMID 33292299, 2020). "Taken together, these results demonstrated that SKP1 promotes YAP-mediated colorectal cancer stemness via suppressing RASSF1 at both mRNA and protein levels." (PMID 33292299, 2020). "RASSF1 and RASSF3 have been considered as potential biomarkers and for the development of new targeted therapies for colorectal cancer." (PMID 32883271, 2020).
non-small cell lung carcinoma (31 papers, 2007 to 2025). A group of at least three distinct histological types of lung cancer, including non-small cell squamous cell carcinoma, adenocarcinoma, and large cell carcinoma. "After this verification step, the PCR-SERS protocol was then applied to detect the methylation levels of p16, MGMT, and RASSF1 in actual plasma samples taken from 48 non-small-cell lung cancer (NSCLC) patients and 51 controls." (PMID 31903158, 2020). "In conclusion, we identified significant associations between seven genes (CDKN2A, RASSF1, MGMT, RARB, DAPK, WIF1 and FHIT) and smoking behavior in non-small cell lung cancer patients." (PMID 25754026, 2015). "The same study also reported that RASSF1, non-small cell lung cancer (NSCLC) tumor suppressor, expression was elevated after T. gondii infection, which indicated that T. gondii infection might be improved NSCLC." (PMID 36341349, 2022). "For example, the hypermethylation of four genes, CDKN2A, cadherin 13 (CDH13), RASSF1, and APC, can be used to predict tumor progression of stage 1 non-small cell lung cancer (NSCLC)." (PMID 27895806, 2016).
breast tumors (28 papers, 2006 to 2023). "Therefore, this can be a reason for the higher-frequency of methylation in RASSF1 relative to other genes in breast tumors." (PMID 27065772, 2016). "Using candidate-gene approach, we examined the promoter methylation level of AR, ESR1, hTERT, MYC, RASSF1 and WNT1 in 69 male breast tumors and corresponding blood samples, 7 normal breast tissues and 8 normal lymph node samples." (PMID 29731982, 2018). "The hypermethylation of RASSF1 and RASSF2 genes was analyzed in 198 breast tumors of different subtypes." (PMID 26284587, 2015). "In particular, we examined promoter methylation status of genes involved in signal transduction and hormone signalling, including AR, ESR1, hTERT, MYC, RASSF1 and WNT in male breast tumors, paired blood samples and normal tissues." (PMID 29731982, 2018).
bladder cancer (26 papers, 2004 to 2025). "Although the role of RASSF1 in bladder cancer development is still unclear, Ha and coworkers reported that its methylation would seem to play a part in predicting recurrence in low grade and stage bladder tumors." (PMID 24252461, 2013). "Several studies have shown that quercetin inhibits cell survival and induces apoptosis of bladder cancer cell lines: This compound also upregulates tumor suppressors by inhibiting CDK inhibitor 2A (CDKN2A) and Ras association domain family member 1A (RASSF1A) gene methylation." (PMID 33996570, 2021).
thyroid cancer (17 papers, 2011 to 2024). "Subgroup analysis according to NOS quality grade for RASSF1 illustrated that studies with a quality of more than 7 yielded more specific thyroid cancer risk factors (OR: 2.67) in comparison with low-quality studies (OR: 7.39)." (PMID 28926589, 2017). "In literature, it has been shown that the methylation status of markers like RASSF1, DAPK1, and ESR1 has been significantly associated with thyroid cancer subtypes and early detection of thyroid cancer." (PMID 32324757, 2020). "The observed significant differential methylation of RASSF1 (p=0.05) in AA vs CA suggests epigenetic influences, offering opportunities for further study to examine the role of DNA methylation in thyroid cancer racial disparities." (PMID 27158284, 2015). "Promoter methylation status of genes with reported associations in thyroid cancer (CASP8, CDKN2A, DAPK1, ESR1, NIS, RASSF1 and TIMP3) were examined in a cohort of follicular thyroid cancers comprising of 26 Hurthle and 27 Classic subtypes utilizing quantitative methylation-specific PCR." (PMID 27158284, 2015). "Overexpression of miR-146b-3p directly targeted NF2, RASSF1, and RASSF5 in thyroid cancer cells and inactivated Hippo signaling, which further promoted anoikis resistance and lymphatic metastasis of thyroid cancer." (PMID 33489905, 2020). "In the current study, our results showed that MAPK8IP1P2 activated Hippo signaling by sponging miR-146b-3p to disrupt targeting effect of miR-146b-3p on NF2, RASSF1, and RASSF5, which inhibited anoikis resistance and lymphatic metastasis of thyroid cancer." (PMID 33489905, 2020). "Collectively, our findings clarify that MAPK8IP1P2 activates Hippo signaling by sponging miR-146b-3p to disrupt the inhibitory effect of miR-146b-3p on NF2, RASSF1, and RASSF5 expression in thyroid cancer." (PMID 33489905, 2020). "Mechanistically, MAPK8IP1P2 activated Hippo signaling by sponging miR-146b-3p to disrupt the inhibitory effect of miR-146b-3p on NF2, RASSF1, and RASSF5 expression, which further inhibited anoikis resistance and lymphatic metastasis in thyroid cancer." (PMID 33489905, 2020). "In the thyroid cancers, CASP8, RASSF1, and NIS were methylated in 9/13, 10/13, and 7/13 respectively." (PMID 21738852, 2011). "CASP8, RASSF1 and NIS were also methylated in concurrently present normal thyroid tissue in 3/11, 4/11 and 3/11 matched thyroid cancer cases (matched for presence of both normal thyroid tissue and thyroid cancer), respectively." (PMID 21738852, 2011). "Mechanistic investigations revealed that MAPK8IP1P2 activated Hippo signaling by sponging miR-146b-3p to disrupt the inhibitory effect of miR-146b-3p on NF2, RASSF1, and RASSF5 expression, which further inhibited anoikis resistance and lymphatic metastasis in thyroid cancer." (PMID 33489905, 2020). "In summary, our results demonstrate that MAPK8IP1P2 activates Hippo signaling by sponging miR-146b-3p as a ceRNA to disrupt the inhibitory effect of miR-146b-3p on NF2, RASSF1, and RASSF5 expression, which further suppresses lymphatic metastasis of thyroid cancer." (PMID 33489905, 2020). "The methylation status of RASSF1, DAPK1 and ESR1 suggests the utility of methylation markers to molecularly differentiate thyroid cancer subtypes for enhanced classification and early detection of thyroid cancer." (PMID 27158284, 2015). "In our study, significant differential methylation of RASSF1 between FTC-Classic and FTC-Hurthle tumor suggests that DNA methylation markers may be useful in discriminating among thyroid cancer subtypes." (PMID 27158284, 2015). "Importantly, miR-146b-3p mimics not only reversed the NF2, RASSF1, and RASSF5 level enhanced by MAPK8IP1P2 overexpression, but also inactivated Hippo signaling in MAPK8IP1P2-overexpressing thyroid cancer cells as indicated by elevated the luciferase reporter activity of HOP-Flash." (PMID 33489905, 2020).
pancreatic cancer (16 papers, 2009 to 2025). "CircHIPK3 overexpression was found to promote gemcitabine (GEM) resistance in pancreatic cancer cells by targeting “RASSF1” through miR-330-5p and was proposed to be a novel biomarker in GEM-resistant PC." (PMID 36230649, 2022). "For instance, the elevated level of circHIPK3 can promote gemcitabine (GEM) resistance in pancreatic cancer cells by targeting RASSF1 via miR-330-5p, while the overexpression of circHIPK3 in bladder cancer (BC) leads to GEM sensitivity." (PMID 33975598, 2021). "CircHIPK3 fostered GEM resistance in pancreatic cancer cells via miR-330-5p/RASSF1 axis." (PMID 33975598, 2021). "The effect of circHIPK3 on gemcitabine resistance is attributed to its negative regulatory role on miR-330-5p which enables RASSF1 activity, favoring proliferation, invasiveness, migration, EMT, and apoptosis inhibition in pancreatic cancer." (PMID 40061896, 2025).
glioma (14 papers, 2006 to 2023). A benign or malignant brain and spinal cord tumor that arises from glial cells (astrocytes, oligodendrocytes, ependymal cells). "RASSF1 is frequently epigenetically inactivated in adult glioma via promoter hypermethylation; restoration of RASSF1 expression sharply restricts glioma cell line colony formation." (PMID 30701019, 2018). "Here, we identify that RASSF1 CGI methylation correlates with hippo pathway inactivation and loss of pS127-YAP1 in sporadic malignancies and provide evidence for the association of this methylation with invasive behavior in cancers, such as breast, bladder, and in gliomas." (PMID 26549256, 2015).
lymph node metastasis (13 papers, 2008 to 2025). "Methylation of RASSF1 (P= 0.012) and GSTP1 (P=0.028) were associated with lymph node metastasis." (PMID 27065772, 2016). "Methylation of GSTP1 (P=0.028) and RASSF1 (P=0.012) were related with lymph node metastasis." (PMID 27065772, 2016).
adenoma (12 papers, 2007 to 2020). A neoplasm arising from the epithelium. "COBRA for RASSF1 has been proven to be correlated with its gene function, and our results were close to theirs (13% in CRCs and 6% in adenomas)." (PMID 17923875, 2007). "Of the 120 adenomas examined, RASSF2 methylation was observed in 30 (25%) cases, while only 3 (2.5%) adenomas exhibited RASSF1 methylation." (PMID 17923875, 2007). "In addition, clinicopathological features of colorectal tumours that carry the methylation of either RASSF1 or RASSF2 are still largely unknown in adenomas as well as in cancers." (PMID 17923875, 2007). "In addition, 2 out of 3 adenomas with RASSF1 methylation also showed methylation of RASSF2." (PMID 17923875, 2007). "In particular, higher methylation levels of CDKN2B, RASSF1, CHFR, BRCA2 and IGSF4 were observed in adenomas that recurred." (PMID 25091577, 2014). "On the other hand, reports regarding the frequency of RASSF1 and RASSF2 methylation in adenomas have been scarce." (PMID 17923875, 2007). "ESR1 has been shown to occur in histologically normal colon epithelium in an age dependent fashion, CDH13 is also frequently methylated in CRC and seems to be correlated with the adenoma-carcinoma transition, like other genes with methylation frequencies > 30% (CDKN2B, RASSF1, RARB, APC and TIMP3)." (PMID 25091577, 2014). "Hypermethylation of RASSF1, a known tumor suppressor gene, has been described in 75% of FTC, a smaller percentage of benign adenomas (44%), and PTC (20%) (Xing, Cohen, Mambo, Tallini, & Udelsman, 2004) indicating that this may be an early step in follicular cell derived thyroid tumorigenesis." (PMID 27158284, 2015). "However, methylation of RASSF1 in colorectal neoplasm was relatively infrequent in our study (3% in adenomas and 12% (data not shown) in CRCs)." (PMID 17923875, 2007).
cervical cancer (11 papers, 2014 to 2026). A primary or metastatic malignant neoplasm involving the cervix.
lung adenocarcinoma (11 papers, 2013 to 2026). A carcinoma that arises from the lung and is characterized by the presence of malignant glandular epithelial cells. "Re‐expression of RASSF1A in H1299 lung adenocarcinoma cells is associated with reduced invasion, metastatic progression and inability to generate cancer stem‐like cells, which provides a rationale for widely reported poor clinical outcomes in RASSF1‐methylated tumours." (PMID 31268606, 2019). "It has been reported that single nucleotide polymorphism at codon 133 of the RASSF1 gene is preferentially associated with human lung adenocarcinoma risk, but not for human lung squamous cell carcinoma." (PMID 23705663, 2013).